MIR8057 (microRNA 8057)
Synonyms: hsa-mir-8057
Gene: MicroRNA gene on chromosome 18 (26,591,467 to 26,591,535, reverse strand). Ensembl gene ENSG00000276221.
Homologues: Orthologues: chimpanzee MIR8057 (100% identical).